ALG8 (ALG8 alpha-1,3-glucosyltransferase)
Description:
Dolichyl pyrophosphate Glc1Man9GlcNAc2 alpha-1,3-glucosyltransferase that operates in the biosynthetic pathway of dolichol-linked oligosaccharides, the glycan precursors employed in protein asparagine (N)-glycosylation. The assembly of dolichol-linked oligosaccharides begins on the cytosolic side of the endoplasmic reticulum membrane and finishes in its lumen. The sequential addition of sugars to dolichol pyrophosphate produces dolichol-linked oligosaccharides containing fourteen sugars, including two GlcNAcs, nine mannoses and three glucoses. Once assembled, the oligosaccharide is transferred from the lipid to nascent proteins by oligosaccharyltransferases. In the lumen of the endoplasmic reticulum, adds the second glucose residue from dolichyl phosphate glucose (Dol-P-Glc) onto the lipid-linked oligosaccharide intermediate Glc(1)Man(9)GlcNAc(2)-PP-Dol to produce Glc(2)Man(9)GlcNAc(2)-PP-Dol. Glc(2)Man(9)GlcNAc(2)-PP-Dol is a substrate for ALG10, the following enzyme in the biosynthetic pathway. Required for PKD1/Polycystin-1 maturation and localization to the plasma membrane of the primary cilia (By similarity).
Synonyms: MGC2840; CDG1H; PCLD3
Tractability: Antibody: UniProt predicts a signal peptide or a membrane-spanning region. PROTAC: ubiquitination databases record sites on it; its protein half-life has been measured.
Target class: Enzyme; Transferase
Gene: Protein-coding gene on chromosome 11 (78,095,244 to 78,139,660, reverse strand). Ensembl gene ENSG00000159063.
Subcellular location: Endoplasmic reticulum membrane
Subcellular location (Human Protein Atlas): Nucleoplasm
Pathways (Reactome):
Disease: Defective ALG8 causes CDG-1h
Metabolism of proteins: Biosynthesis of the N-glycan precursor (dolichol lipid-linked oligosaccharide, LLO) and transfer to a nascent protein
Gene Ontology:
Molecular function: dolichyl pyrophosphate Glc1Man9GlcNAc2 alpha-1,3-glucosyltransferase activity; protein binding; dolichyl-phosphate-glucose-glycolipid alpha-glucosyltransferase activity; hexosyltransferase activity
Biological process: dolichol-linked oligosaccharide biosynthetic process; protein N-linked glycosylation
Cellular component: endoplasmic reticulum membrane; lumenal side of endoplasmic reticulum membrane
Genetic constraint (gnomAD): Loss-of-function variants: 42 observed, 59.79 expected, observed/expected ratio (o/e) 0.7, 90% interval 0.55 to 0.91. The upper end of that interval is the gene's LOEUF score, 0.91, which puts it in group 3 of 6, group 1 being the genes least tolerant of losing a copy. Missense variants: 531 observed, 558.45 expected, observed/expected ratio (o/e) 0.95, 90% interval 0.88 to 1.02. Synonymous variants: 209 observed, 209.01 expected, observed/expected ratio (o/e) 1, 90% interval 0.89 to 1.12.
Gene-disease validity (ClinGen):
ClinGen rates the evidence that ALG8 causes each of these diseases.
autosomal dominant polycystic kidney disease (autosomal dominant): Definitive. Autosomal dominant form of polycystic kidney disease.
Homologues: Orthologues: chimpanzee ALG8 (99% identical), pig ALG8 (94% identical), dog ALG8 (93% identical), macaque ALG8 (90% identical), rabbit ALG8 (90% identical), mouse Alg8 (90% identical), guinea pig ALG8 (89% identical), rat Alg8 (88% identical), tropical clawed frog alg8 (70% identical), zebrafish alg8 (68% identical), Drosophila melanogaster xit (48% identical), Caenorhabditis elegans algn-8 (36% identical). Paralogues in human: ALG6 (25% identical).
Diseases named in the same sentence as ALG8 in open-access papers:
ALG8 is named in the same sentence as 56 diseases in open-access papers, as found by Europe PMC text mining. Sharing a sentence is not in itself a finding about the gene and the disease. The quoted sentences say what the papers report.
liver cysts (5 papers, 2022 to 2025). "The loss of function in a single ALG8 allele is associated with the development of hepatic cysts (ALG8-PLD (OMIM #617874))." (PMID 37628703, 2023). "The immunohistochemistry of his liver cyst tissue demonstrated the complete loss of the ALG8 protein in the cyst wall." (PMID 37628703, 2023). "DY2242 II-1 had ALG8 c.175-2A>G variant and abdominal CT showing bilateral polycystic kidney disease with liver cysts at the age of 44 with preserved kidney function." (PMID 35778421, 2022). "Overall, ALG8-associated PLD possesses the ADPLD phenotype with hepatic cysts, but patients may also develop renal cysts, which can mimic early-stage ADPKD." (PMID 37628703, 2023). "ALG8 was another gene involved in the development of kidney and liver cysts, even though the severity of the disease was mild." (PMID 39928271, 2025). "ALG6 strongly resembles ALG8 which has been implicated in kidney and liver cyst phenotypes, and according to KidneyNetwork, ALG6 and ALG8 are highly co-regulated (z-score = 8.59)." (PMID 36807342, 2023). "Her father does not carry a pathogenic variant in ALG8 but has three hepatic cysts, the largest being 2.7 cm." (PMID 37628703, 2023). "In addition to ALG8, ALG9 heterozygous variants have recently also been implicated in the etiology of kidney and liver cyst phenotypes." (PMID 36807342, 2023). "Family segregation of the variant [chr11:77812084-T-C; c.1507 A > G; p.(Ile503Val)] in the ALG8 gene revealed the presence of the same variant in his daughter, who also suffers from renal cysts but, at least till the time of analysis, without liver cysts." (PMID 38012624, 2023). "DY1920 I-2 was diagnosed with ALG8 p.Gly275fs mutation, her kidney cysts rarely extended outside the kidney contour with no liver cyst at the age of 65." (PMID 35778421, 2022). "The lack of association between ALG8 variants and liver cysts may arise from the composition of their cohort, as polycystic kidneys (1:1500) are more prevalent than polycystic livers (<1:10,000) in the general population." (PMID 37628703, 2023). "Unrelated individuals, or even family members, with the same pathogenic ALG8 variant do not have a similar degree of ADPLD severity, and some only have a small number of hepatic cysts." (PMID 37628703, 2023). "Interestingly, while kidney or liver cysts have been described, among multi-organ involvement in fetuses or children with ALG9-CDG or infrequently in ALG8-CDG, cysts have not been described for ALG6-CDG." (PMID 36807342, 2023).
Renal cyst (5 papers, 2020 to 2025). A fluid filled sac in the kidney. "Protein-truncating variants in α-1,3-glucosyltransferase (ALG8) are a risk factor for a mild cystic kidney disease phenotype." (PMID 37628703, 2023). "ALG8-associated ADPLD has a broad clinical spectrum, including the possibility of developing a small number of renal cysts." (PMID 37628703, 2023). "ALG8 was recently described as a very rare cause of ADPLD, but at least one patient had renal cysts at a young age." (PMID 32457805, 2020). "Additionally, ALG8 has also been identified in cystic kidney disease (≥4 kidney cysts) without any PLD connection, and in ADPLD with multiple kidney cysts." (PMID 37628703, 2023).
breast carcinoma (4 papers, 2007 to 2021). "Previous studies have shown that ALG8 could be a variate of prognostic model for gastric adenocarcinoma and frequently amplified hotspot on 11q14.1 (ALG8) associated with significantly worse prognosis for breast cancer." (PMID 34692502, 2021). "Expression levels of ALG1, ALG2, ALG3, ALG8, ALG9, ALG12 and ALG13 were differentially upregulated in radioresistant breast cancer tissues compared with those in radiosensitive tissues, particularly ALG3 with the highest level (4.53-fold change)." (PMID 33931075, 2021). "GISTIC identifies a peak encompassing four genes (THRSP, NDUFC2, ALG8 and KCTD21), amplification of which have been shown in breast cancer to correlate with over-expression and poor survival." (PMID 20844748, 2010).
polycystic kidney (4 papers, 2017 to 2023). "ALG6, similarly to established polycystic kidney and liver disease gene ALG8, is a member of the α3-glucosyltransferase family." (PMID 36807342, 2023). "Defects in the N-linked glycosylation genes ALG3, ALG8, and ALG9, as well as the O-linked glycosylation gene B3GALTL, variably result in polycystic kidneys, cleft lip or palate, polycystic ovaries, and abnormal development of the brain including the corpus callosum." (PMID 28344780, 2017). "The phenotype in the genetically unsolved polycystic kidney and liver patients we identified to carry ALG6 variants is relatively mild, in many cases liver predominant and asymptomatic, consistent with the phenotype described for patients carrying a heterozygous ALG8 or ALG9 pathogenic variant." (PMID 36807342, 2023).
congenital disorder of glycosylation (3 papers, 2012 to 2023). Congenital disorder of glycosylation (CDG) is a fast growing group of inborn errors of metabolism characterized by defective activity of enzymes that participate in glycosylation (modification of proteins and other macromolecules by adding and processing of oligosaccharide side chains). "ALG8 is an alpha-1,3-glucosyltransferase and ALG8-CGD (congenital disorders of glycosylation) is a widely studied monogenic disorder of glycosylation that involves multisystem disorders." (PMID 36611197, 2023).
Kidney Cyst (3 papers, 2022 to 2024). Abnormal fluid filled sac within the kidney, either acquired or congenital. "In patients with the diagnosis of PKHD1, ALG8, and GANAB variants, kidney cysts tend to be less destructive than PKD1 and PKD2 with relatively preserved kidney contours." (PMID 35778421, 2022). "In conclusion, pathogenic variants in ALG8 are also associated with ADPLD, and those affected possess no or only a few kidney cysts." (PMID 37628703, 2023).
liver disease (3 papers, 2021 to 2023). "The authors classified CDG based on liver involvement into two main groups: one with predominant/isolated liver involvement (MPI-CDG, CCDC115-CDG, TMEM199-CDG, ATP6AP1-CDG) and the other associated with liver disease (PMM2-CDG, ALG1-CDG, ALG3-CDG, ALG8-CDG, ALG9-CDG, PGM1-CDG)." (PMID 34291020, 2021). "Other CDG, such as ALG8-CDG (MIM: #603147), can present with severe liver disease with cirrhosis and complications of portal hypertension, with high lethality." (PMID 33413482, 2021).
autosomal dominant polycystic liver disease (2 papers, 2022 to 2023). An autosomal dominant inherited condition characterized by many cysts of various sizes scattered throughout the liver. "We aim to identify pathogenic ALG8 variants in our cohort of autosomal dominant polycystic liver disease (ADPLD) individuals." (PMID 37628703, 2023). "Autosomal Dominant Polycystic Liver Disease (ADPLD) leads to PLD only and is caused by a mutation in PRKCSH, SEC63, LRP5, ALG8 or SEC61B." (PMID 35216547, 2022).
cyst (2 papers, 2021 to 2023). A sac-like closed membranous structure that may be empty or contain fluid or amorphous material. "The three patients with a pathogenic variant in the N-terminal side of ALG8 all had one small cyst on their left kidney (8826, 9173, and 8515)." (PMID 37628703, 2023). "In patient 11698, the ALG8 protein is no longer present in the cholangiocytes or the cells bordering the cyst." (PMID 37628703, 2023).
gastric cancer (2 papers, 2022 to 2023). A primary or metastatic malignant neoplasm involving the stomach. "In malignancies, ALG8 was a variate of a risk predictive model established for gastric cancer and ovarian cancer." (PMID 36611197, 2023). "It has been reported that ALG8 could perform as a variate of a prognostic model for gastric cancer." (PMID 35281472, 2022).
sarcoma (2 papers, 2021). A usually aggressive malignant neoplasm of the soft tissue or bone. "To determine whether Tvax could induce T cell responses to naturally occurring cancer neoantigens, we expressed the Alg8 and Lama4 neoantigens identified in a methylcholanthrene-induced sarcoma fused to the LLO190 epitope and GFP in a retroviral construct." (PMID 34396986, 2021).
acute myeloid leukemia (1 paper, 2007). Acute myeloid leukemia (AML) is a group of neoplasms arising from precursor cells committed to the myeloid cell-line differentiation. "The genes on cytoband 11q14.1, NDUFC2, ALG8 and USP35, also reside close to what appears to be a novel amplicon in acute myeloid leukemias (AML)." (PMID 17925008, 2007).
cataract (1 paper, 2015). Partial or complete opacity of the crystalline lens of one or both eyes that decreases visual acuity and eventually results in blindness. "Unlike other CDG types, cataracts (ocular findings) have only been reported in ALG8-CDG, ALG12-CDG, other subtypes in early LLO synthesis (like SRD5A3-CDG) and some unclassified CDG." (PMID 26066342, 2015). "ALG8-CDG (= CDG-Ih) is one of the less frequently reported types of CDG, maybe due to its severe multi-organ involvement with coagulation disturbances, edema, massive gastrointestinal protein loosing enteropathy, cataracts, and often early death." (PMID 26066342, 2015).
cholestasis (1 paper, 2017). Impairment of the bile flow caused by obstruction within the liver, or outside the liver in the bile duct system. "In CDG presenting with cholestasis (such as ALG8-CDG, COG6-CDG, COG7-CDG, CCDC115-CDG and ATP6AP1-CDG), nutritional interventions such as in other causes of cholestasis can be necessary." (PMID 29112118, 2017).
Cirrhosis (1 paper, 2023). A chronic disorder of the liver in which liver tissue becomes scarred and is partially replaced by regenerative nodules and fibrotic tissue resulting in loss of liver function. "Apoptosis is critical in liver fibrosis and cirrhosis development, a phenotype seen in homozygous ALG8-CDG." (PMID 37628703, 2023).
congenital cataracts (1 paper, 2015). "Here, we describe three severely affected neonates from two families with ALG8-CDG with congenital cataracts, and provide an update on two previously reported children with congenital cataracts, where ALG8-CDG was confirmed recently." (PMID 26066342, 2015).
cystic liver disease (1 paper, 2023). Cystic disease of the liver is rare and can take several forms. "In order to address the potential role of ALG8 in cystic liver disease, we performed a comprehensive effort to discover pathogenic ALG8 variants in a specific ADPLD population." (PMID 37628703, 2023).
depressive disorder (1 paper, 2012). A melancholy feeling of sadness and despair. "Among the cognate genes, six including ALG8, DGKE, GNA12, KLF11, LRPAP1, and MMAB are related to multiple genetic diseases such as depressive disorder and Type-II diabetes." (PMID 22348086, 2012).
intellectual disabilities (1 paper, 2025). "For example, alpha-1,3-glucosyltransferase- (ALG8-) CDG has been found to show intellectual disabilities besides other organ manifestations including musculoskeletal, dermatologic and cardiac symptoms." (PMID 40301838, 2025).
Thrombocytopenia (1 paper, 2025). A reduction in the number of circulating thrombocytes. "Notably, thrombocytopenia has also been described in various other types of CDG, including ALG1-, ALG8-, GALE-, GNE-, MPI-, PMM2-, and B4GALT1-CDG." (PMID 40613041, 2025).
tumor (5 papers, 2010 to 2024). "Amplification of 8q24.11-13 (THRAP6, DCC1, SQLE, SPG8) and 11q14.1 (NDUFC2, ALG8, USP35) have been associated with poor prognosis in a novel subtype of high-grade ER- tumors." (PMID 20932292, 2010). "The Wilcoxon rank-sum test showed that ALG8 (P < 0.001) had a higher expression level in tumor tissues compared with normal tissues, while DCTN4 (P < 0.001), DCTN6 (P < 0.001), and UBB (P < 0.001) had lower expression levels in tumor tissues." (PMID 35281472, 2022).
cancer (4 papers, 2012 to 2023). A tumor composed of atypical neoplastic, often pleomorphic cells that invade other tissues. "In summary, except for ALG8, other five GTs are all key enzymes that involves in the synthesis of cancer associated glycans and may exist a close tie between each other." (PMID 36611197, 2023). "Indeed, several glycosylation factors, namely ALG8, ALG3, COLGATLT1, B4GALT3 and DPM2, show increased expression levels in these and other cancers." (PMID 36009354, 2022).
infection (2 papers, 2016 to 2019). The state of being infected such as from the introduction of a foreign agent such as serum, vaccine, antigenic substance or organism. "The genes involved in alginate biosynthesis (algD and alg8) and export (algE) increased throughout the infection." (PMID 31541159, 2019).
neurodevelopmental disorder (1 paper, 2025). A behavioral and cognitive disorder with onset during the developmental period that involves impaired or aberrant development of intellectual, motor, or social functions. "For instance, variants in genes such as ALG8 or ALG9 often result in a complex neurodevelopmental disorder of glycosylation." (PMID 41255767, 2025).
ALG8 also shares sentences with these, for which no sentence is quoted: epilepsy (2 papers); ovarian carcinoma (2); Alzheimer disease (1); autoimmune disease (1); Birk-Landau-Perez syndrome (1); brachydactyly (1); ceruloplasmin deficiency (1); congenital myasthenic syndrome (1); coronary artery disease (1); COVID-19 (1); cryptorchidism (1); dyslipidemia (1); enteropathy (1); epileptic encephalopathies (1); fructose intolerance (1); gastric adenocarcinoma (1); genetic diseases (1); hemochromatosis type 1 (1); kidney disorder (1); kidney stones (1); Lesch-Nyhan syndrome (1); liver fibrosis (1); lymphoma (1); major depressive disorder (1); mucopolysaccharidosis type 2 (1); multiple kidney cysts (1); neuronal ceroid lipofuscinosis (1); Obesity (1); polycystic ovaries (1); scoliosis (1).
A further 2 diseases each share a sentence with ALG8 in 1 paper.